PGR (progesterone receptor)
Diseases named in the same sentence as PGR in open-access papers (continued):
Sharing a sentence is not in itself a finding about the gene and the disease.
triple-negative breast carcinoma (continued). "Triple-negative breast cancer, immunohistochemically defined by lack of expression of estrogen receptor (ER), progesterone receptor (PR), and human epidermal growth factor receptor 2 (HER2), is an important phenotype of breast cancer that accounts for approximately 10–15% of all breast cancers." (PMID 23049873, 2012). "However, the basal-like category is composed almost entirely of triple-negative breast cancers (TNBCs) (i.e., tumors lacking ER, progesterone receptor (PgR) and HER2 expression)." (PMID 18950515, 2008). "Triple-negative breast cancer is one of the most lethal human cancers characterized by the high aggressiveness and heterogeneity and absence of the expression of estrogen receptor (ER), progesterone receptor (PR), and human epidermal growth factor receptor 2 (HER2)." (PMID 38194043, 2024). "Triple-negative breast cancers (TNBCs) are an aggressive subtype of breast cancer constituting 10–15% of all breast cancers and are defined by the lack of expression of estrogen receptor (ER), progesterone receptor (PR), and the human epidermal growth factor receptor 2 (HER2)." (PMID 34526485, 2021). "Notably, an estimated 60–69% of triple negative breast cancers (with absence of oestrogen receptor (ER) progesterone receptor (PR) as well as nonamplified HER2) are reported to have a defect in DNA repair, with features in common with BRCA1/2 mutated tumors described as “BRCAness”." (PMID 31320901, 2019). "Among various breast cancer subtypes, triple-negative breast cancer (TNBC) is notable for the absence of estrogen receptor (ER), progesterone receptor (PR), and human epidermal growth factor receptor 2 (HER2)." (PMID 41554761, 2026). "Triple-negative breast cancer (TNBC), an aggressive subtype lacking estrogen receptor (ER), progesterone receptor (PR), and HER2 expression, accounts for 10-20% of breast cancers and is characterized by high metastatic potential and poor survival outcomes." (PMID 42099744, 2026). "Triple-negative breast cancer (TNBC) is an aggressive subtype characterized by the lack of estrogen receptor (ER), progesterone receptor (PR), and HER2 expression, making it unresponsive to traditional therapies." (PMID 40266550, 2026). "Triple-negative breast cancer (TNBC) is an aggressive subtype of breast cancer characterized by the lack of estrogen receptor (ER), progesterone receptor (PR), and human epidermal growth factor receptor 2 (HER2)." (PMID 39980537, 2025). "Triple-negative breast cancer (TNBC) is characterized by the absence of estrogen receptor, progesterone receptor, and human epidermal growth factor receptor 2, contributing to its aggressive nature, limited treatment options, and poor prognosis." (PMID 40416168, 2025). "Triple-negative breast cancer (TNBC) is a clinically aggressive subtype defined by the absence of estrogen receptor (ER), progesterone receptor (PR), and HER2 expression, leaving few targeted therapeutic options." (PMID 41156777, 2025). "The cardinal features of triple-negative breast cancer (TNBC) are that it is aggressive and does not express estrogen receptor, progesterone receptor, and human epidermal growth factor receptor 2, presenting significant therapeutic challenges." (PMID 41249701, 2025). "Triple-negative breast cancer (TNBC) is an aggressive subtype defined by the absence of estrogen receptor, progesterone receptor, and HER2 expression." (PMID 41169398, 2025). "Triple-negative breast cancer (TNBC) is characterized by the absence of estrogen receptor (ER), progesterone receptor (PR), and HER2, and is a histologically and prognostically heterogeneous disease." (PMID 39851328, 2025). "Triple-negative breast cancer (TNBC) is a distinct and aggressive subtype of breast cancer, characterized by the absence of estrogen receptor (ER), progesterone receptor (PR), and human epidermal growth factor receptor 2 (HER2) expression." (PMID 40248551, 2025).
triple-negative breast carcinoma (continued). "Triple-negative breast cancer (TNBC) is characterized by the lack of ESR (estrogen receptor) and PGR (progesterone receptor) expression and the absence of ERBB2/HER2 (erb-b2 receptor tyrosine kinase 2) overexpression or gene amplification." (PMID 40097917, 2025). "Triple-negative breast cancer (TNBC) is an aggressive subtype of breast cancer characterized by the lack of estrogen receptor (ER), progesterone receptor (PR), and human epidermal growth factor receptor 2 (HER2) expression." (PMID 41009462, 2025). "Triple-negative breast cancer (TNBC) is an aggressive and clinically challenging subtype defined by the absence of estrogen receptor, progesterone receptor, and HER2 amplification, resulting in poor prognosis and limited therapeutic options." (PMID 41123660, 2025). "On the other hand, basal-like or triple-negative breast cancers (TNBC) do not express estrogen receptor (ER), progesterone receptor (PR), and HER2." (PMID 40940399, 2025). "Triple-negative breast carcinoma (TNBC) is a biologically and clinically heterogeneous group of tumors defined by the absence of estrogen receptor (ER), progesterone receptor (PR), and HER2 expression." (PMID 41301002, 2025). "MCA is usually a negative expression for estrogen receptor (ER), progesterone receptor (PR), and human epidermal growth factor receptor-2 (HER-2), hence classified as triple-negative breast cancer (TNBC)." (PMID 39757664, 2025). "Triple-negative breast cancer (TNBC) is defined by the lack of estrogen receptor (ER), progesterone receptor (PR), and human epidermal growth factor receptor 2 (HER2) expression." (PMID 41169398, 2025). "Most BRCA1 carriers develop triple-negative breast cancer (TNBC)—estrogen receptor (ER)-, progesterone receptor (PR)-, and HER2 -negative cancers—which originates from ER/PR/HER2-negative breast progenitor cells." (PMID 41283387, 2025). "Triple-negative breast cancer (TNBC) is a highly aggressive subtype of breast cancer (BRCA) characterized by the absence of estrogen receptor (ER), progesterone receptor (PR), and human epidermal growth factor receptor 2 (HER2) expression." (PMID 40606662, 2025). "ER estrogen receptor, DCIS ductal carcinoma in situ, HER2 human epidermal growth factor receptor 2, NST no special type, IQR interquartile range, PR progesterone receptor, TNBC triple-negative breast cancer." (PMID 40764352, 2025). "Of these, the so-called ‘triple-negative breast carcinoma’ (TNBC) marked by the absence of estrogen receptor (ER) and progesterone receptor (PgR) expression, as well as the lack of human epidermal growth factor receptor 2 (HER2) protein overexpression." (PMID 39695043, 2025). "Triple-negative breast cancer (TNBC) is a clinically and molecularly distinct subtype of breast cancer defined by the absence of estrogen receptor (ER), progesterone receptor (PR), and human epidermal growth factor receptor 2 (HER2) expression." (PMID 41008798, 2025). "About 15 to 20 percent of breast tumors are triple-negative breast cancers (TNBC), which are defined by the absence of the progesterone receptor (PR), estrogen receptor (ER) and human epidermal growth factor receptor 2(HER2)." (PMID 39980560, 2025). "Triple-negative breast cancer (TNBC), distinguished by the absence of ER, progesterone receptor (PR) and HER2 expression, comprises approximately 15% of all diagnosed breast cancers worldwide." (PMID 40705122, 2025). "Triple-negative breast cancer (TNBC) is recognized as the most aggressive form of breast cancer and is defined by the lack of expression of estrogen receptor (ER), progesterone receptor (PR), and human epidermal growth factor receptor 2 (HER2)." (PMID 40869161, 2025). "The triple-negative breast cancer (TNBC) subclass accounts for 15 - 20% of all BCs and does not express the estrogen receptor (ER), progesterone receptor (PR), or human epidermal growth factor receptor 2 (Her-2)." (PMID 41234389, 2025).
triple-negative breast carcinoma (continued). "Triple-negative breast cancer (TNBC), defined by the absence of estrogen receptor (ER), progesterone receptor (PR), and human epidermal growth factor receptor 2 (HER2), represents one of the most clinically challenging subtypes of breast cancer." (PMID 41278869, 2025). "Triple-negative breast cancer (TNBC) is an aggressive subtype characterized by the absence of estrogen receptor (ER), progesterone receptor (PR), and human epidermal growth factor receptor 2 (HER2) expression." (PMID 41142826, 2025). "Triple-negative breast cancer (TNBC) is characterized by the absence of estrogen receptor (ER), progesterone receptor (PR), and HER-2 amplification, rendering it unresponsive to endocrine and HER2-targeted therapies." (PMID 41422171, 2025). "Triple negative breast cancer (TNBC), accounting for approximately 15% of all BC cases, is characterised by the absence of the oestrogen receptor (ER), progesterone receptor (PR) and lack of amplification of the human epidermal growth factor receptor 2 (HER2)." (PMID 41148819, 2025). "Clinically, the type of breast cancer with the worst prognosis is the triple negative breast cancer (TNBC, Human epidermal growth factor receptor 2 (HER2)-negative/Progesterone receptor (PR)-negative/Estrogen receptor (ER)-negative)." (PMID 40869256, 2025). "Triple-negative breast cancer (TNBC) is a subtype of breast cancer characterized by the absence of estrogen receptor (ER), progesterone receptor (PR), and human epidermal growth factor 2 (HER2) receptors." (PMID 41188939, 2025). "In contrast, triple-negative breast cancer (TNBC) presents a distinct profile, characterized by the absence of estrogen receptor, progesterone receptor, and ErbB2 expression." (PMID 39908697, 2025). "Triple-negative breast cancers (TNBC) are an aggressive subtype, characterized by a lack of estrogen receptor (ER), progesterone receptor (PR) and human epidermal growth factor receptor 2 (HER2) expression." (PMID 40034592, 2025). "Triple-negative breast cancer (TNBC) is considered the most challenging type, as it is defined by an absence of estrogen and progesterone receptor expression, along with a lack of HER2 overexpression." (PMID 40005083, 2025). "Triple-negative breast cancer (TNBC) is a highly aggressive subtype characterized by the absence of estrogen receptor (ER), progesterone receptor (PR), and human epidermal growth factor receptor 2 (HER2) expression." (PMID 39473450, 2024). "Triple-negative breast cancer (TNBC) is defined by the absence of the estrogen receptor (ERα), progesterone receptor (PR), and the human epidermal growth factor receptor-2 (ERBB2/HER2) in tumor cells." (PMID 39171293, 2024). "MBC is generally oestrogen receptor (ER) negative, progesterone receptor (PgR) negative and human epidermal growth factor receptor 2 (HER2) negative, categorized as triple-negative breast carcinoma (TNBC)." (PMID 38564036, 2024). "Triple-negative breast cancer (TNBC) constitutes 12–17% of all BCs and it is characterized by the lack of estrogen receptor (ER), progesterone receptor (PR) and human epidermal growth factor receptor 2 (HER2) expression." (PMID 38468323, 2024). "Basal-like breast cancer (BLBC) is a specific category of invasive BC, and most BLBC are triple-negative breast cancers (TNBC), which are negative for estrogen receptor (ER), progesterone receptor (PR), and human epidermal growth factor receptor 2 (HER-2)." (PMID 39513107, 2024). "Triple-negative breast cancer (TNBC) has the absence of three receptors on the surface of tumor cells: ER (estrogen receptor), PR (progesterone receptor), and HER2 (human epidermal growth factor receptor 2)." (PMID 38773471, 2024). "Triple-negative breast cancer (TNBC) is defined as the absence of estrogen receptor (ER), progesterone receptor (PR), and epidermal growth factor receptor 2 (HER2)." (PMID 39563370, 2024).
triple-negative breast carcinoma (continued). "Triple-negative breast cancer (TNBC) is a subtype of breast cancer that presents significant therapeutic challenges due to the absence of estrogen receptor (ER), progesterone receptor (PR), and human epidermal growth factor receptor 2 (HER2) expression." (PMID 38933280, 2024). "Breast cancers lacking the expression of estrogen receptor (ER), progesterone receptor (PR), and human epidermal growth factor receptor 2 (HER2) are referred to as triple-negative breast cancers (TNBC)." (PMID 39272726, 2024). "Triple-negative breast cancer (TNBC) is characterized by the absence of estrogen receptor (ERα), progesterone receptor (PR), and human epidermal growth factor receptor 2 (HER2) expression." (PMID 39614393, 2024). "The typical subtypes include breast cancers that express oestrogen receptor (ER) and/or progesterone receptor (PR), those expressing HER2, or triple negative breast cancer (TNBC), characterised by the absence of these receptors." (PMID 39596057, 2024). "Triple-negative breast cancer (TNBC) is characterized by a lack of estrogen receptor (ER), progesterone receptor (PR) and HER2 expression." (PMID 38594783, 2024). "Triple-negative breast cancer (TNBC), a subgroup of breast cancer defined by the lack of expression of oestrogen receptor, progesterone receptor, and human epidermal growth factor receptor 2, accounts for 15 to 20%." (PMID 39624628, 2024). "Triple-negative breast cancer (TNBC) is an aggressive disease characterized by the lack of expression of estrogen receptor (ER), progesterone receptor (PR), and HER2/neu receptor (HER2)." (PMID 38315150, 2024). "This correlation was also evident in triple-negative breast cancer (TNBC), the most aggressive subtype of breast cancer characterized by the absence of Estrogen Receptor (ER), Progesterone Receptor (PR), and HER2." (PMID 39690159, 2024). "The basal-like subtype is for 80% defined as triple-negative breast cancer (TNBC), characterised by the absence of oestrogen receptor (ER), progesterone receptor (PR), and human epidermal growth factor receptor 2 (HER2) expression." (PMID 38817965, 2024). "Triple-negative breast cancer (TNBC) represents a distinct subtype characterized by the absence of the estrogen receptor (ER), progesterone receptor (PR), and human epidermal growth factor receptor type 2 (HER2)." (PMID 39519023, 2024). "Based on biomarker expression, pathological analyses define malignancies as positive for estrogen receptor (ER), progesterone receptor (PR), and HER2, or as negative for all three markers (triple-negative breast cancer, TNBC)." (PMID 38571887, 2024). "Triple-negative breast cancer (TNBC) is an aggressive subtype characterized by the absence of estrogen receptor, progesterone receptor, and human epidermal growth factor receptor type 2 expression." (PMID 39065715, 2024). "Triple negative breast cancer (TNBC) has its name due to its negative expression of estrogen receptor (ER), progesterone receptor (PR), and human epidermal growth factor receptor 2 (HER2)." (PMID 39138583, 2024). "Triple-negative breast cancer (TNBC) is widely known as the absence of estrogen receptor (ER), progesterone receptor (PR), and human epidermal growth factor receptor-2 (HER2) expressions, which makes it a lack of targets for precise and effective treatment." (PMID 39268503, 2024). "Triple-negative breast cancer (TNBC) is characterized by the absence of the estrogen receptor, progesterone receptor, and receptor tyrosine kinase HER2 expression." (PMID 38791148, 2024). "Triple-negative breast cancer (TNBC) is a distinct subtype characterized by the absence of estrogen receptor (ER), progesterone receptor (PR), and human epidermal growth factor receptor 2 (HER2) expression." (PMID 39741315, 2024). "Pathological findings of breast metastases are often negative for ER, PgR, and HER2 status, so cases of triple negative breast cancer are often diagnosed differently." (PMID 39292386, 2024).
triple-negative breast carcinoma (continued). "We also tested the binding of the bsAb to MDA-MB-231, a triple-negative breast cancer (TNBC) cell line (negative for the estrogen receptor, progesterone receptor, and HER2) with a low HER2 level." (PMID 39066446, 2024). "Triple-negative breast cancer (TNBC) is characterized by lack of the estrogen (ER) receptor, progesterone receptor (PR), and human epidermal growth factor receptor-2 (HER2), and standard receptor-targeted therapies are ineffective." (PMID 39171293, 2024). "Triple-negative breast cancer (TNBC) is a breast cancer subtype characterized by the absence of estrogen receptor (ER), progesterone receptor (PR), and human epidermal growth factor receptor 2 (HER-2) expression." (PMID 37875918, 2023). "Triple-negative breast cancer (TNBC), which is defined by the lack of estrogen receptor (ER), progesterone receptor (PR), and human epidermal growth factor receptor 2 (HER2) expression, accounts for 15–20% of all breast cancers." (PMID 37958571, 2023). "Triple-negative breast cancer (TNBC) is characterized by the absence of estrogen receptor (ER), progesterone receptor (PR), and human epidermal growth factor receptor 2 (HER-2) expression." (PMID 37854685, 2023). "Triple-negative breast cancers (TNBC) are malignant tumors characterized by a lack of estrogen receptor (ER) and progesterone receptor (PR) expression and human epidermal growth factor receptor 2 (HER2)/neu overexpression." (PMID 37298528, 2023). "The term “triple-negative breast cancer” (TNBC) refers to a kind of BC in which the Human Epidermal Growth Factor Receptor 2 (HER-2), Progesterone Receptor (PR), and Estrogen Receptor (ER) are not expressed in the tumors." (PMID 36771058, 2023). "Triple-negative breast cancers (TNBC) are defined as breast cancers without the expression of estrogen receptor (ER), progesterone receptor (PR), and human epidermal growth factor receptor 2 (HER2)." (PMID 37792212, 2023). "Among its diverse subtypes, triple-negative breast cancer (TNBC) is characterized by the absence of estrogen receptor (ER), progesterone receptor (PR), and human epidermal growth factor receptor 2 (HER-2) expression." (PMID 38030604, 2023). "Triple negative breast cancer (TNBC) is defined as lacking the expressions of estrogen receptor (ER), progesterone receptor (PR), and human epidermal growth factor receptor 2 (HER2)." (PMID 37932309, 2023). "Triple-negative breast cancer (TNBC) lacks the estrogen receptor (ER), progesterone receptor (PR), and HER2 receptor and therefore does not respond to endocrine therapy or anti-Her2 therapy, resulting in poor prognosis." (PMID 37438419, 2023). "Triple-negative breast cancer (TNBC) refers to an aggressive subtype of breast case with negative results of estrogen receptor (ER), progesterone receptor (PR), and proto-oncogene Her-2 in immunohistochemical examination of cancer tissue." (PMID 37660121, 2023). "Triple-negative breast cancer (TNBC) is phenotypic of breast tumors lacking expression of the estrogen receptor (ER), the progesterone receptor (PgR), and the human epidermal growth factor receptor 2 (HER2)." (PMID 37432459, 2023). "Triple-negative breast cancer (TNBC) is another BCa subtype characterized by the absence of and HER2 expression, estrogen receptor (ER), and progesterone receptor (PR)." (PMID 38111570, 2023). "Triple-negative breast cancer (TNBC) is a subset of breast cancer characterized by the absence of estrogen receptor (ER), progesterone receptor (PR), and HER-2 expression." (PMID 37586771, 2023). "Triple-negative breast cancer (TNBC), characterized by the absence of estrogen receptor (ER), progesterone receptor (PR) and human epidermal growth factor receptor 2 (HER2) expression, accounting for about 15-20% of breast cancers." (PMID 37208633, 2023).